IKBKE (inhibitor of nuclear factor kappa B kinase subunit epsilon)
Description:
Serine/threonine kinase that plays an essential role in regulating inflammatory responses to viral infection, through the activation of the type I IFN, NF-kappa-B and STAT signaling. Also involved in TNFA and inflammatory cytokines, like Interleukin-1, signaling. Following activation of viral RNA sensors, such as RIG-I-like receptors, associates with DDX3X and phosphorylates interferon regulatory factors (IRFs), IRF3 and IRF7, as well as DDX3X. This activity allows subsequent homodimerization and nuclear translocation of the IRF3 leading to transcriptional activation of pro-inflammatory and antiviral genes including IFNB. In order to establish such an antiviral state, IKBKE forms several different complexes whose composition depends on the type of cell and cellular stimuli. Thus, several scaffolding molecules including IPS1/MAVS, TANK, AZI2/NAP1 or TBKBP1/SINTBAD can be recruited to the IKBKE-containing-complexes. Activated by polyubiquitination in response to TNFA and interleukin-1, regulates the NF-kappa-B signaling pathway through, at least, the phosphorylation of CYLD. Phosphorylates inhibitors of NF-kappa-B thus leading to the dissociation of the inhibitor/NF-kappa-B complex and ultimately the degradation of the inhibitor. In addition, is also required for the induction of a subset of ISGs which displays antiviral activity, may be through the phosphorylation of STAT1 at 'Ser-708'. Phosphorylation of STAT1 at 'Ser-708' also seems to promote the assembly and DNA binding of ISGF3 (STAT1:STAT2:IRF9) complexes compared to GAF (STAT1:STAT1) complexes, in this way regulating the balance between type I and type II IFN responses. Protects cells against DNA damage-induced cell death. Also plays an important role in energy balance regulation by sustaining a state of chronic, low-grade inflammation in obesity, wich leads to a negative impact on insulin sensitivity. Phosphorylates AKT1.
Synonyms: IKK-E; IKK-i; IKKE; IKKI; KIAA0151
Tractability: Small molecule: a high-quality ligand is known; it belongs to a druggable protein family. PROTAC: UniProt records ubiquitination sites on it; ubiquitination databases record sites on it; a small molecule that binds it is known.
Target class: Enzyme; Kinase; Protein Kinase; Other protein kinase group
Chemical probes: BAY-985 (high quality), GSK8612 (high quality)
Safety:
Unwanted effects reported when the protein is acted on. In parentheses: how it was acted on, where the effect was seen, and who reports it.
cardiac arrhythmia (cardiovascular system; source: Lamore et al. (2017))
diarrhea (source: ClinPGx)
skin rash (source: ClinPGx)
Gene: Protein-coding gene on chromosome 1 (206,470,332 to 206,496,891, forward strand). Ensembl gene ENSG00000263528.
Subcellular location: Cytoplasm; Nucleus; Nucleus, PML body
Subcellular location (Human Protein Atlas): Cytosol
Pathways (Reactome):
Immune System: Activation of IRF3, IRF7 mediated by TBK1, IKKε (IKBKE); Negative regulators of DDX58/IFIH1 signaling; Regulation of TBK1, IKKε (IKBKE)-mediated activation of IRF3, IRF7; Regulation of TBK1, IKKε-mediated activation of IRF3, IRF7 upon TLR3 ligation; TICAM1-dependent activation of IRF3/IRF7; TRAF3-dependent IRF activation pathway; TRAF6 mediated IRF7 activation
Disease: Dengue virus activates/modulates innate and adaptive immune responses; SARS-CoV-1 activates/modulates innate immune responses; SARS-CoV-2 activates/modulates innate and adaptive immune responses
Signal Transduction: Regulation of TNFR1 signaling; TNFR1-induced proapoptotic signaling
Cellular responses to stimuli: Turbulent (oscillatory, disturbed) flow shear stress activates signaling by PIEZO1 and integrins in endothelial cells
Metabolism of proteins: SUMOylation of immune response proteins
Gene Ontology:
Molecular function: identical protein binding; IkappaB kinase activity; K48-linked polyubiquitin modification-dependent protein binding; K63-linked polyubiquitin modification-dependent protein binding; protein binding; protein serine/threonine kinase activity; ubiquitin protein ligase binding; protein phosphatase binding; ATP binding; protein kinase activity
Biological process: intrinsic apoptotic signaling pathway in response to DNA damage; positive regulation of canonical NF-kappaB signal transduction; positive regulation of type I interferon production; positive regulation of type I interferon-mediated signaling pathway; response to interferon-beta; activation of innate immune response; defense response to virus; immune response; positive regulation of lipid storage; type I interferon-mediated signaling pathway; cellular response to virus; gene expression; interleukin-17-mediated signaling pathway; intracellular signal transduction; mRNA stabilization; regulation of protein-containing complex assembly; response to cytokine; response to stress; response to type I interferon
Cellular component: cytoplasm; cytosol; mitochondrial membrane; nucleus; PML body; nucleoplasm; serine/threonine protein kinase complex
Genetic constraint (gnomAD): Loss-of-function variants: 41 observed, 80.69 expected, observed/expected ratio (o/e) 0.51, 90% interval 0.4 to 0.66. The upper end of that interval is the gene's LOEUF score, 0.66, which puts it in group 2 of 6, group 1 being the genes least tolerant of losing a copy. Missense variants: 664 observed, 893.79 expected, observed/expected ratio (o/e) 0.74, 90% interval 0.7 to 0.79. Synonymous variants: 365 observed, 369.51 expected, observed/expected ratio (o/e) 0.99, 90% interval 0.91 to 1.08.
Homologues: Orthologues: chimpanzee IKBKE (100% identical), macaque IKBKE (98% identical), pig IKBKE (89% identical), dog IKBKE (89% identical), guinea pig IKBKE (85% identical), mouse Ikbke (83% identical), rat Ikbke (80% identical), tropical clawed frog ikbke (58% identical), zebrafish ikbke (48% identical), Drosophila melanogaster IKKepsilon (35% identical). Paralogues in human: TBK1 (49% identical), CHUK (20% identical), IKBKB (20% identical).
Diseases named in the same sentence as IKBKE in open-access papers:
IKBKE is named in the same sentence as 150 diseases in open-access papers, as found by Europe PMC text mining. Sharing a sentence is not in itself a finding about the gene and the disease. The quoted sentences say what the papers report.
viral infection (65 papers, 2009 to 2026). "IKBKE-deficient mice are viable, although they are hypersusceptible to some viral infections, whereas TBK1-knockout mice die at embryonic day 15 from TNF-induced apoptosis in the liver." (PMID 37937644, 2023). "To further verify the role of CALCOCO2 in the replication of EV71 and FMDV, we evaluated the viral infection-induced degradation of IKBKE and viral replication in CALCOCO2-/- HEK-293T cells." (PMID 41319264, 2026). "Additionally, we examined the subcellular localization of SVA VP2 and IKBKE in the context of viral infection." (PMID 41319264, 2026). "The IKBKE protein is a key adapter in antiviral innate immune signaling, phosphorylating IRF3 and promoting the production of type I IFN to combat viral infections." (PMID 41319264, 2026). "However, the detailed cellular/molecular mechanisms explaining why the IKBKE c.312delC variant resulted in recurrent HSV-2 meningitis and no other severe manifestations of viral infections remain elusive." (PMID 37937644, 2023).
breast carcinoma (43 papers, 2010 to 2025). "IKKε is overexpressed in most breast cancers and in 30% of cases this is associated with amplification of sequences on the long arm of human chromosome 1, including the IKKε gene, IKBKE." (PMID 21646685, 2011). "Given that breast cancer is a heterogenous disease, commonly classified into 5 to 10 intrinsic subtypes, the association of IKBKE and PSAT1 might be driven by subtype‐specific expression." (PMID 32783398, 2020). "Being also closely linked to the pathogenesis of breast cancer by promoting activation of NF-κB, targeting IKBKE may be an interesting future perspective for developing new treatment strategies against cervical cancer." (PMID 28767691, 2017). "Previous studies have shown that IKBKE is associated with inflammatory responses and metabolic diseases and is highly expressed in various malignant tumors, including non-small cell lung cancer, renal clear cell carcinoma, breast cancer, ovarian cancer, and glioma." (PMID 41378297, 2025). "High matrix stiffness (5 kPa) promoted higher IKBKE protein expression in human breast cancer CA1a and HCC1143 cells, as compared to low stiffness (0.5 kPa)." (PMID 40468448, 2025). "The knockdown efficiency of the four individual IKBKE siRNAs, which are mixed to form the IKBKE siRNA pool, was tested in human breast cancer HCC1143 cells." (PMID 40468448, 2025). "Conditional expression of microRNA-155 in breast cancer models highlighted its suppression of IKKε (IKBKE) expression, followed by down-regulation of NF-κB signaling, a process also modulated by PAX5." (PMID 40506992, 2025). "The inhibitor of nuclear factor kappa B kinase subunit epsilon (IKKε) is involved in the regulation of the stem cell phenotype in breast cancer cells." (PMID 36142160, 2022). "Inhibitor of nuclear factor κ B kinase subunit ε (IKBKE) had been discovered as an oncogene and is overexpressed in over 30% of breast carcinomas samples and cell lines." (PMID 33682883, 2021). "In prior studies, IKBKE has been demonstrated to be a novel oncogene in breast cancer and was shown to be amplified in over 30% of breast cancer cases." (PMID 34544426, 2021). "Williams et al83 identified a novel association between IKBKE and EGFR expression (P = .0011) using ICH (immunohistochemistry) analysis in breast cancer specimens, and knockdown of IKBKE using siRNA decreases the expression of EGFR." (PMID 31733040, 2020). "Boehm et al25 found that IKBKE was highly expressed in 30% of breast cancer specimens and 16.3% of breast cancer cell lines through analysis of integrative genomic approaches, thus first identifying IKBKE as a new oncogene in breast cancer." (PMID 31733040, 2020). "The IKBKE gene is located on chromosome 1q, which is frequently amplified in breast cancer, partly explaining overexpression of the kinase." (PMID 31930708, 2020). "Silencing of IKBKE reduced proliferation, clonogenicity, migration and invasion of breast cancer cells." (PMID 29801480, 2018). "Increased protein levels seen with pharmacological ΙΚΚε inhibition were confirmed using an siRNA against IKBKE (siIKKε) in the panel of breast cancer cells that express high endogenous IKKε." (PMID 29801480, 2018). "Inhibiting IKBKE can promote breast cancer cell apoptosis and cell transformation through activation of the NF-κB pathway." (PMID 28548934, 2017). "Future clinical trials may evaluate the repurposing of Amlexanox as well as the efficacy of other IKBKE inhibitors in breast cancer treatment." (PMID 40468448, 2025). "Hence, the implication of IKBKE in breast carcinoma became a promising prospect for targeted therapies." (PMID 35955463, 2022). "Furthermore, they also demonstrated that IKBKE functions downstream of AKT2 to promote breast cancer cell survival." (PMID 31733040, 2020).
breast carcinoma (continued). "Li et al28 demonstrated that IKBKE interacted with ER‐α36 (estrogen receptor‐α), a novel variant of ER‐α, and increased its expression in breast cancer cells, enhancing ER‐α36‐mediated mitogenic and nongenomic estrogen signaling." (PMID 31733040, 2020). "Furthermore, Qin et al26 showed that IKBKE knockdown in human breast cancer cells using siRNA resulted in an obvious reduction of tumor cell proliferation, migration, and invasion." (PMID 31733040, 2020). "Eddy et al24 showed that IKBKE was highly expressed in human breast cancer specimens and several breast cancer cell lines, which hinted that IKBKE might regulate the growth of breast cancer in some ways." (PMID 31733040, 2020). "Li et al28 demonstrated that IKBKE interacted with ERα‐36, which lacks intrinsic transcriptional activity and, in contrast with ERα, mediated mainly nongenomic estrogen signaling; it also has increased expression in breast cancer cells." (PMID 31733040, 2020). "In addition, several regulatory genes in the IL-17 signaling pathway, such as TNFAIP3, TRADD, and IKBKE, were also observed to be correlated with PD-1 and/or PD-L1 in one or more cohorts of breast cancer samples." (PMID 33102239, 2020). "In addition, increased IKBKE expression was observed at the transcriptional and translational levels in numerous breast cancer cell lines and breast cancer specimens, but expression was not absolutely correlated with DNA copy number changes." (PMID 31733040, 2020). "Furthermore, Tang et al29 identified IKBKE as a direct target of miR‐16, and overexpression of miR‐16 promoted taxol‐induced cytotoxicity and apoptosis in breast cancer cells via decreasing IKBKE expression." (PMID 31733040, 2020). "Analysis of epithelial breast cancer cell lines and primary breast tumors showed copy-number gain or amplification of the 1q32 region resulting in up to 10 copies of the IKBKE locus encoding for IKKε." (PMID 28532474, 2017). "The Toll-like pathway protein IKBKE (IKKε), which is reportedly amplified and overexpressed in breast cancer cell lines and patient-derived tumors, similarly suppresses IKKε expression in breast cancer cell lines that harbor IKKε amplifications, inducing cell death." (PMID 22216095, 2011). "Similarly, our study points to IKBKE signaling in breast cancer progression, specifically in driving DCIS to IDC transition, and further suggests that IKBKE is activated as a result of augmented mechanical signaling, adding yet another layer of regulation of this kinase in breast cancer cells." (PMID 40468448, 2025). "Furthermore, treatment of IKBKE‐driven breast cancer cells with a potent inhibitor of TBK1/IKBKE and JAK signaling impaired proliferation and colony formation of TNBC cells, whereas inhibition of JAK alone did not, suggesting that IKBKE regulated tumor cell progression." (PMID 31733040, 2020). "We validated the function of the predicted kinases using RNAi-based screening and identified the IKBKE and MAPK8 kinases as mechanoregulated proteins being potential targets for development of novel breast cancer treatment." (PMID 40468448, 2025). "In conclusion, we show that matrix stiffness activates several tyrosine and serine/threonine kinases and validated two of these kinases, IKBKE and MAPK8, as critical for a malignant breast cancer cell phenotype." (PMID 40468448, 2025). "Further validation of the IKBKE inhibitor was performed in HCC1143 cells, and also in these cells, the Amlexanox treatment inhibited the stiffness-induced malignant breast cancer cell phenotype (top row) and proliferation (bottom row)." (PMID 40468448, 2025). "The IKBKE-inhibitor Amlexanox, clinically utilized for aphthous ulcers, as well as the MAPK8 inhibitor JNK-IN-8, reinstalled the DCIS-like phenotype of breast cancer cells on high matrix stiffness." (PMID 40468448, 2025). "For example, IKBKE phosphorylates CYLD and TRAF2 in breast cancer cells, which induces NF-κB activation and contributes to cell transformation." (PMID 34544426, 2021).
breast carcinoma (continued). "The importance of IKBKe in driving tumor malignancy potential in both TNBC and receptor positive breast cancer cells are known." (PMID 28441391, 2017). "One of the identified kinases, inhibitor of nuclear factor kappa-B kinase subunit epsilon (IKBKE), a non-canonical I-kappa-B kinase, has been identified as a breast cancer oncogene amplified and overexpressed in more than 30% of breast carcinomas." (PMID 40468448, 2025). "This suggests that IKBKE and/or MAPK8 inhibitors could enhance the arsenal of treatments to prevent or treat breast cancer." (PMID 40468448, 2025). "Increased expression of IKBKE in cancer has been detected both with and without corresponding copy number gain and several recent studies implicate this kinase in breast cancer progression and metastasis." (PMID 40468448, 2025). "This suggests that IKBKE and/or MAPK8 inhibitors could play a role in future breast cancer prevention and treatment." (PMID 40468448, 2025). "Furthermore, Barbie et al27 found that treatment of IKBKE‐driven breast cancer cells with CYT387, a potent inhibitor of TBK1/IKBKE and JAK signaling, reduced the proliferation and migration of TNBC cells, whereas inhibition of JAK alone does not." (PMID 31733040, 2020). "After phosphorylation by IKBKE, FOXO3a was deprived of the ability to induce tumor cell apoptosis due to its retention and degradation in the cytoplasm, thus accelerating the progression of NSCLC and breast cancer cells." (PMID 31733040, 2020). "In breast cancer cell lines, Krishnamurthy et al75 found that AKT could regulate TNF‐dependent IKBKE expression levels." (PMID 31733040, 2020). "IKBKE was indicated as a potential oncogene by phosphorylating inhibitors of NFKB to prolong cell survival, and its amplifications and over-expressions were seen in over 30% of breast cancer patients and cell lines." (PMID 21935476, 2011). "In addition, the tumor cell cycle was arrested at the G0/G1 phase after silencing IKBKE by flow cytometry analysis, while IKBKE knockdown did not seem to significantly affect apoptosis in breast cancer cells." (PMID 31733040, 2020). "Indeed, a recent study demonstrated that inducible IκB kinase-related (IKK-related) kinase IKBKE promotes in triple negative breast cancer cells the expression of IL-6 and CCL5, which in turn sustain the proliferation and migration of breast cancer cells in 3D culture." (PMID 29707128, 2018). "Chemical or RNAi-mediated inhibition of IKBKE or FER did not result in specific cytotoxicity, indicating that their inhibition is not sufficient to explain the specificity toward basal-like breast cancer cell lines." (PMID 25699542, 2015).
Obesity (28 papers, 2013 to 2024). Accumulation of substantial excess body fat. "Previous study had demonstrated that IKBKE knockout attenuated inflammation and had a protective effective against diet-induced obesity." (PMID 28273165, 2017).